BSG (basigin (Ok blood group))
Diseases named in the same sentence as BSG in open-access papers (continued):
Sharing a sentence is not in itself a finding about the gene and the disease.
cancer (continued). "It is well-documented that both ADAM12 and BSG promote cancer progression, at least in part by regulating integrin and MMP activity." (PMID 38892056, 2024). "The basigin gene (BSG), also known as CD147, has been implicated in the progression and prognosis of various cancers, including liver cancer." (PMID 39006665, 2024). "BSG mRNA level was significantly upregulated in 7 cancer types, including ACC, ESCA, KICH, LIHC, PAAD, SKCM and THYM, however, was significantly downregulated in LAML." (PMID 38484369, 2024). "To gain more insights into BSG in multiple human cancers, we explored the expression level of BSG and prognostic value across pan-cancers." (PMID 38484369, 2024). "These individual BSG isoforms have been found to exert distinct regulatory effects in the context of cancer." (PMID 39006665, 2024). "These evidences indicated an essential role of BSG for SARS-CoV-2 entry in cancer patients through the lungs." (PMID 38484369, 2024). "BSG also known as Basigin or CD147, EMMPRIN, an immunoglobulin member, which can interact with extracellular, intracellular and membrane proteins and is the first reported protein to promote cancer development." (PMID 38114725, 2023). "Intriguingly, top five upregulated genes are all linked to regulation of oncogenesis and metastasis and pan cancer analysis of TCGA dataset revealed that these genes have co-occurrence of expression in cancers including CRYAB with BSG and HELLS." (PMID 36624493, 2023). "Our study revealed differences in the BSG expression levels in various human organs and cancer cells." (PMID 35646943, 2022). "In 12 of 20 cancers in this study, BSG demonstrated pronounced effects in identifying cancer tissues from their control counterparts (AUC >0.7)." (PMID 35646943, 2022). "Another function of BSG that is important in cancer is its stimulatory effect on angiogenesis by inducing the expression of the pro-angiogenic vascular endothelial growth factor (VEGF)." (PMID 35054026, 2022). "Based on the correlation analysis, BSG expression was negatively (ρ < -0.3, p < 0.05) correlated with at least ten checkpoints in seven cancers (CHOL, KICH, KIRC, PAAD, THCA, THYM, and UVM)." (PMID 35646943, 2022). "Especially in CHOL, KICH, and LIHC, the AUC values were more than 0.95, suggesting that BSG expression made it feasible to distinguish these cancers and implying the significant potential of BSG expression to predict these cancers." (PMID 35646943, 2022). "BSG expression showed a pronounced effect in identifying multiple cancers (e.g., CHOL) from their control samples." (PMID 35646943, 2022). "Under the microscope, the staining intensity of the anti-BSG antibodies in the ten cancer tissues was observed to be stronger than that in normal tissues." (PMID 35646943, 2022). "CD147 (basigin, BSG) is a membrane-bound glycoprotein involved in energy metabolism that plays a role in cancer cell survival." (PMID 35723405, 2022). "In the observed 20 cancer types, the BSG expression levels of 16 cancers differed from those of the corresponding control samples." (PMID 35646943, 2022). "BSG is not only differently expressed in most tumors but represents different prognosis results and identifies cancer status in some cancers." (PMID 35646943, 2022). "An analysis based on CCLE data demonstrated the different distribution of BSG in various cancer cell lines (p < 0.05)." (PMID 35646943, 2022). "Among the 16 cancers listed earlier, BSG protein levels were investigated in ten types as there were at least two cancer samples and two normal samples for the ten." (PMID 35646943, 2022). "BSG expression is increased in many cancers, and it is considered to be a biomarker for cancer diagnosis and prognosis." (PMID 35054026, 2022). "For the top seven essential signaling pathways (olfactory transduction, etc.)presenting statistical significance in at least four cancers, correlations of their leading-edge genes with BSG expression were explored." (PMID 35646943, 2022).
cancer (continued). "Using UALCAN, we performed pan-cancer expression, finding that BSG exhibited a high level in many types of tumors based on the TCGA data sets." (PMID 33654226, 2022). "In a word, BSG promoted the cancer cell invasion and development of TC via regulating MMPs and affecting ECM." (PMID 32891152, 2020). "Previous studies have shown that BSG played an important role in cancers, but which mechanisms it used to promote the occurrence and development of TC?" (PMID 32891152, 2020). "BSG has also been verified as a potential stimulator of matrix metalloproteinases (MMPs) and is considered to be a prognostic marker in cancer." (PMID 32891152, 2020). "BSG is upregulated in several types of tumors, and soluble BSG concentrations in blood or urine from cancer patients correlate with disease stage and poor prognosis." (PMID 31013576, 2019). "For example, it appears that soluble BSG, shed from the cell surface of cancer cells, acts in a paracrine manner to stimulate the expression of MMP2 in the surrounding stromal fibroblast." (PMID 31013576, 2019). "Although MCT/BSG complex targeting therapies have shown great efficacy in several cancer cell lines, questions regarding their toxicity to normal tissues require further investigation." (PMID 26099350, 2016). "We have also recently reported functional residual MCT1 and MCT4 expression in different BSG-null cancer cell lines, suggesting the presence of unidentified proteins or mechanisms for targeting these MCTs to the cell surface." (PMID 26099350, 2016). "Further investigation of CD44 expression in BSG-null mice and cancer cell lines should be performed to understand the implication of this receptor in lactate transport." (PMID 26099350, 2016). "Due to the interdependency of MCT1/4 and BSG for functional expression of lactate transport, and also to the key role of this glycoprotein in cancer development, it seems evident to consider BSG as a promising therapeutic target in cancer." (PMID 26099350, 2016). "Both the SCP2 and BSG branches share the same CAV1 upstream regulators such as MAPK3, TNFRSF1B, and GNAI2, which have been implicated in cancer cells death pathways." (PMID 24949431, 2014). "Thus, TMPRSS11B expression is reciprocal to the highly malignant reverse Warburg cells expressing SLC16A1 and BSG, giving rise to relapse-forming and also metastasizing cancers." (PMID 40508207, 2025). "Together, in cancer microenvironments, an interdependent system of glucose/pyruvate/lactate energy metabolism is in place that affects the cellular redox status and modulates BSG/SLC16 monocarboxylate transport." (PMID 40508207, 2025). "And each isoform of BSG has distinct expression levels in different cancer types." (PMID 38484369, 2024). "Moreover, BSG stimulates cancer cell invasion through mechanisms involving the interaction with cell-surface β1 integrin." (PMID 38892056, 2024). "Mechanistically, BSG overexpression can induce angiogenesis, activate matrix metalloproteinases to degrade extracellular matrix, promote cancer cell invasion, and inhibit cancer cell anoikis (cell death after detachment)." (PMID 39006665, 2024). "In addition, we investigated the expression of BSG and its isoforms in multiple malignancies and adjacent normal tissues, and explored the prognostic values across pan-cancers." (PMID 38484369, 2024). "Overexpression of BSG correlates with poor prognosis in malignant tumors, which suggest that BSG may promote coronavirus infection in patients with malignancies." (PMID 38484369, 2024). "Therefore, we compared the expression level of ACE2, HSPA5, BSG in pan-cancers based on TCGA datasets." (PMID 38484369, 2024). "Moreover, in four cases of paired cancer and adjacent tissues, the expression rate of BSG in cancer tissues was significantly higher compared with that in adjacent tissues." (PMID 38484369, 2024).
cancer (continued). "Moreover, in five cases of paired cancer and adjacent tissues, the expression of BSG in cancer tissues was significantly higher compared with that in adjacent tissues." (PMID 38484369, 2024). "In cancer cell lines, BSG mRNA expression was up-regulated when compared to normal cells." (PMID 38484369, 2024). "The relationship between them with BSG expression was explored in the 15 cancers." (PMID 35646943, 2022). "Totally, 39 KEGG signaling pathways were found for BSG in 32 cancers in this study." (PMID 35646943, 2022). "We also analyzed the correlation between PPIA and BSG expression in pan-cancer using cBioPortal." (PMID 36012604, 2022). "In at least five cancers, BSG was shown closely related to three pathways—olfactory transduction, metabolism of xenobiotics by cytochrome P450, and hematopoietic cell lineage indicating the gene may play its roles in multiple human cancers." (PMID 35646943, 2022). "We investigated the prognosis value of BSG expression in various cancers." (PMID 35646943, 2022). "BSG may play its role in several cancers by affecting several signaling pathways such as drug cytochrome metabolism P450 and JAK-STAT." (PMID 35646943, 2022). "Based on drug sensitivity, our research also revealed that some drugs might be applied to cancer patients with high expression of BSG, but more effort is also needed to confirm these results further." (PMID 35646943, 2022). "However, BSG expression and its relation with clinical relevance and immune infiltration levels in pan-cancer were rarely reported, which requires further investigation." (PMID 35646943, 2022). "Notably, high-BSG expression was sensitive to 12 (e.g., KPT-8602 and brigatinib) of the 57 drugs, suggesting the potential of these drugs in treating cancer patients with elevated BSG expression." (PMID 35646943, 2022). "Moreover, the associations of BSG expression with TMB, MSI, neoantigen, and immune checkpoints suggested the potential of BSG as an exciting target for cancer treatment." (PMID 35646943, 2022). "Collectively, differential (mainly increasing) BSG expression was observed in various cancers." (PMID 35646943, 2022). "Additionally, many previous researchers have studied the relationship between BSG and human cancers and further confirmed the role of BSG in the development of human tumors." (PMID 32891152, 2020). "Like BSG, several of the ADAMs play important roles in cancer." (PMID 31013576, 2019). "However, the functional relevance of the correlation between ADAM12 and BSG in cancer remains elusive." (PMID 31013576, 2019). "CD147, encoded by BSG, is a highly glycosylated transmembrane protein that belongs to the immunological superfamily and expressed on the surface of many types of cancer cells." (PMID 29560120, 2018). "In short, BSG may be a novel target for cancer treatment and identification." (PMID 35646943, 2022). "Basigin (BSG) is an essential factor for the infection and progression of COVID-19 and tumorigenesis of multiple tumors, which may serve as a novel target for the effective treatment against COVID-19 and multiple human cancers." (PMID 35646943, 2022). "BSG may be an important potential target for treating various cancers." (PMID 35646943, 2022). "Furthermore, the expression of PPIA and BSG was positively correlated in many cancers." (PMID 36012604, 2022). "The role of BSG in cancer suggests that it could be an effective therapeutic target." (PMID 32891152, 2020). "Notably, FUT11, BGLAP, SSR2, TGFBR1, BSG, and FUCA1 have been reported to be associated with related cancer, but no studies showed the functions of other eight DESPGs in corresponding cancers." (PMID 31824949, 2019). "Our results support a TNBC model whereby in older cohorts, myeloid cells and CAFs interact with cancer basal cells via LGALS9/P4HB, PPIA/BSG and PLAU/PLAUR signaling to promote EMT and cell motility." (PMID 41188599, 2025).
cancer (continued). "More importantly, several cell adhesion proteins, such as BSG, ITGA2, CD9, SLC3A2 or CD151, were significantly enriched in TuNEPs and shared across cancer types." (PMID 40751052, 2025). "In the older TNBC cohort, myeloid cells and CAFs interact with cancer basal cells through LGALS9/P4HB, PPIA/BSG, and PLAU/PLAUR ligand/receptor pairs to promote EMT and cell motility, as confirmed by the age-related increase in EMT ARPs." (PMID 39483921, 2024). "Of these, BSG/CD147, HEBP2, HSD17B12, and GNB2L1/RACK1 have well characterised functions in cancer and cell survival." (PMID 38398114, 2024). "Due to the vital role played by lysosomes in cancer, a LRRS signature was constructed, including 8 genes, namely, CLN3, GBA, CTSA, BSG, APLN, SORT1, ANXA2, and LAPTM4B." (PMID 38114725, 2023). "Thus, BSG may serve as a marker for predicting the disease status of certain cancers." (PMID 35646943, 2022). "Hence, anti-CD147/BSG- and CD147-related inhibitors that may regulate the immune system as novel antitumor drugs or antiangiogenic agents have been developed and used for the treatment of cancer." (PMID 35603157, 2022). "Subsequently, we analyzed the relationship between the cancer stage and the expression levels of PPIA and BSG using UALCAN." (PMID 36012604, 2022). "Among these genes, BSG, which is also known as CD147, is a key gene involved in the development and progression of cancers." (PMID 35132181, 2022). "Upregulated and downregulated BSG expression was observed in 14 cancers (BRCA, etc.)and two cancers (COAD and READ), respectively." (PMID 35646943, 2022). "We were the first show colocalization of CD147 (BSG) and CD318 (CDCP1) at the surface of cancer cell line expressing KRas4B mutant." (PMID 34611477, 2021). "Nonetheless, our identification of PPIA-induced cellular BSG expression has important implications for cancer progression in regard to the relationships between PPIA, BSG, and MMPs." (PMID 22631225, 2012). "In addition, it was shown by promoter analysis that the expression of many cancer stem cell (CSC)-related genes such as TERT, BMI1, BSG (CD147), and PROM1 (CD133) was under the control of SP1, HIF1A, and MYC." (PMID 39590335, 2024). "Although there is no statistical significance for other cancers, a trend can be seen that upregulation of BSG protein levels was identified in BLCA, BRCA, LUAD, LUSC, PRAD, and STAD (p > 0.05)." (PMID 35646943, 2022). "As a result, the significant (positive or negative) relevance of BSG expression with the 21 leading-edge genes was identified in certain types of the 15 cancers based on the Spearman rank correlation analysis (p < 0.05)." (PMID 35646943, 2022). "Additionally, an analysis of cancer stages revealed a significant correlation between the expression levels of SLC3A2, BSG, SLC7A5, SLC7A6, LCN2, and SLC7A9 and the pathological stages of ACC, with p-values of 0.28, 0.468, 0.00799, 0.0237, 0.0359, 0.264, 0.193, 0.81, and 0.0246, respectively." (PMID 40566559, 2025). "Thus, proteolytic cleavage of the Ig-C2/Ig-I domain of BSG may lead to an altered conformation of the BSG/SLC16A3 and BSG/SLC16A1 conformation, supporting a forced export of lactate as a prerequisite for enhanced glycolysis and cancer cell growth." (PMID 40508207, 2025). "In short, the biological functions of BSG in specific cancers may attribute to its negative correlation with the immune microenvironment." (PMID 35646943, 2022). "Additionally, the adjustment tests were carried out for KICH, LIHC, and BRCA as BSG expression was detected related to no less than two clinical parameters in the three cancers." (PMID 35646943, 2022). "However, overexpression of LDHA, CAIX, MCT4, and BSG has only been reported in other types of cancer, but not in CC." (PMID 36678382, 2022).
cancer (continued). "As a result, BSG expression showed that it was significantly related to the five MMRs in multiple cancers, especially in UVM and GBM, implying that BSG may affect the expression of MMRs in certain cancers, which needs experimental validation." (PMID 35646943, 2022). "The immediate relevance of BSG expression with AJCC stages was found in HNSCC, KICH, LIHC, PAAD, SKCM, and THCA (p < 0.05), while such a phenomenon was not in the other cancers (ACC, etc.)." (PMID 35646943, 2022). "First, using three human cancer cell lines, LS174, A549, and U87 (wt versus BSG−/−), we showed that BSG gene disruption did not significantly affect the MMPs production in extracellular media." (PMID 26284589, 2015). "Moreover, reverse Warburg areas in PDAC patient-derived cancer tissues were identified by high SLC16A1 and BSG expression but absence of TMPRSS11B expression." (PMID 40508207, 2025). "Being essential for the heterogeneity of many malignant tumors, these reverse Warburg cancer cells might differentially contribute to malignant progression depending on the presence of SLC16A1 and BSG as well as the absence of TMPRSS11B." (PMID 40508207, 2025). "In terms of gender, males with BRCA or KIRP had overexpression of BSG, while the contrast phenomenon was found in patients with KICH or LIHC (p < 0.05); and for other cancers (ACC, etc.), there was no statistical difference in BSG expression between patients with different genders." (PMID 35646943, 2022). "In the aspect of immune infiltration levels, BSG expression showed a negative correlation with nearly all six types of immune cells (B cells, CD4+ T cells, CD8+ T cells, neutrophil, macrophage, and dendritic cells) in THCA, CHOL, and SKCM (p < 0.05) rather than other cancers." (PMID 35646943, 2022).